OR8K5 (olfactory receptor family 8 subfamily K member 5)
Description:
Odorant receptor.
Synonyms: OR11-174
Tractability: Antibody: UniProt places it where antibodies can reach, with medium confidence; UniProt predicts a signal peptide or a membrane-spanning region; its Gene Ontology location is reachable by antibodies, with medium confidence.
Gene: Protein-coding gene on chromosome 11 (56,159,394 to 56,160,317, reverse strand). Ensembl gene ENSG00000181752.
Subcellular location: Cell membrane
Pathways (Reactome):
Sensory Perception: Expression and translocation of olfactory receptors
Gene Ontology:
Molecular function: olfactory receptor activity; G protein-coupled receptor activity
Biological process: G protein-coupled receptor signaling pathway; sensory perception of smell; detection of chemical stimulus involved in sensory perception of smell
Cellular component: plasma membrane; membrane
Genetic constraint (gnomAD): Missense variants: 425 observed, 378.01 expected, observed/expected ratio (o/e) 1.12, 90% interval 1.04 to 1.22. Synonymous variants: 149 observed, 138.73 expected, observed/expected ratio (o/e) 1.07, 90% interval 0.94 to 1.23.
Homologues: Orthologues: pig OR8K5 (84% identical), dog OR8K5 (82% identical), rat Or8k16b (77% identical), mouse Or8k21 (76% identical), rat Or8k16 (76% identical), mouse Or8k16 (75% identical). Paralogues in human: OR8K3 (70% identical), OR8K1 (64% identical), OR8J2 (58% identical), OR8U3 (58% identical), OR8J1 (57% identical), OR8J3 (57% identical), OR8U1 (57% identical), OR5B12 (53% identical), OR8D4 (51% identical), OR5B21 (50% identical), OR8D1 (50% identical), OR9G4 (50% identical), and 84 more.